C1orf105 (chromosome 1 open reading frame 105)
Tractability: No criterion of Open Targets' tractability assessment is met for any kind of drug.
Gene: Protein-coding gene on chromosome 1 (172,420,685 to 172,468,831, forward strand). Ensembl gene ENSG00000180999.
Subcellular location (Human Protein Atlas): Vesicles
Gene Ontology:
Molecular function: protein binding
Genetic constraint (gnomAD): Loss-of-function variants: 4 observed, 10 expected, observed/expected ratio (o/e) 0.4, 90% interval 0.2 to 0.92. The upper end of that interval is the gene's LOEUF score, 0.92, which puts it in group 3 of 6, group 1 being the genes least tolerant of losing a copy. Missense variants: 171 observed, 163.07 expected, observed/expected ratio (o/e) 1.05, 90% interval 0.93 to 1.19. Synonymous variants: 54 observed, 57.58 expected, observed/expected ratio (o/e) 0.94, 90% interval 0.75 to 1.18.
Homologues: Orthologues: chimpanzee C1H1orf105 (98% identical), macaque C1H1orf105 (92% identical), pig C1orf105 (71% identical), rabbit C1orf105 (67% identical), dog C7H1orf105 (58% identical), mouse 4930558K02Rik (58% identical), rat C13h1orf105 (57% identical).
Diseases named in the same sentence as C1orf105 in open-access papers:
C1orf105 is named in the same sentence as 6 diseases in open-access papers, as found by Europe PMC text mining. Sharing a sentence is not in itself a finding about the gene and the disease. The quoted sentences say what the papers report.
atherosclerosis (2 papers, 2020 to 2022). A disease characterized by the build-up of fatty material and calcium deposition in the arterial wall resulting in partial or complete occlusion of the arterial lumen. "A previous study reported that the C1orf105 gene was associated with the remodeling response to atherosclerosis." (PMID 36295481, 2022). "Previous study showed that a SNP on C1orf105 was associated with remodeling response to atherosclerosis." (PMID 32682418, 2020).
atrial fibrillation (2 papers, 2022 to 2024). A disorder characterized by an electrocardiographic finding of a supraventricular arrhythmia characterized by the replacement of consistent P waves by rapid oscillations or fibrillatory waves that vary in size, shape and timing and are accompanied by an irregular ventricular response. "While of unknown function, C1orf105 has been associated with heart failure, atrial fibrillation (Afib), and CAD by genome-wide association studies (GWAS)." (PMID 38978787, 2024). "Finally, five genes (FRZB, SFRP4, ETNPPL, AQP4, C1orf105) were found to be highly co-expressed in patients with heart failure and atrial fibrillation." (PMID 36295481, 2022).
cardiovascular disease (2 papers, 2020 to 2022). "In summary, the hub genes related with M2 macrophages that we searched include CCL22, C1orf105, GAP43, and PTPN21, all of which imply a relationship with cardiovascular disease, which is consistent with our findings." (PMID 36222281, 2022).
cancer (1 paper, 2021). A tumor composed of atypical neoplastic, often pleomorphic cells that invade other tissues. "Among the key genes, C1ORF105 was associated with a larger inter-adventitial common carotid artery diameter (ICCAD), and FAM132b can be increased by induction of erythrogenesis, suggesting that they may play an important role in the occurrence and development of cancer." (PMID 34026368, 2021).
C1orf105 also shares sentences with these, for which no sentence is quoted: heart failure (2 papers); abdominal aortic aneurysm (1).